EZH2 (enhancer of zeste 2 polycomb repressive complex 2 subunit)
Diseases named in the same sentence as EZH2 in open-access papers (continued):
Sharing a sentence is not in itself a finding about the gene and the disease.
tumor (continued). "Preclinical studies have demonstrated that BRG1 inactivation increases tumor invasiveness and enhances sensitivity to targeted agents inhibiting oxidative phosphorylation and drugs targeting EZH2, AURKA, ATR, CDK4, and CDK6." (PMID 39465834, 2024). "While current studies focus on the oncogenic role of EZH2, there is evidence for a tumor suppressive function of EZH2 in cancer immunity." (PMID 40135141, 2024). "LOXL1-AS1 has been studied mainly as an oncogenic lncRNA, implicated in tumor growth and development through sponging tumor suppressor miRNAs and, or interacting with proteins and transcription factors such as DESC1 and EZH2." (PMID 39136001, 2024). "As previously discussed, EZH2 is a key regulator of tumor angiogenesis, as it is able to modulate the release of several angiogenic factors, including VEGF, eNOS, and TGFβ, through direct or indirect mechanisms." (PMID 39204206, 2024). "Immune suppression driven by EZH2 is also observed in bladder cancer, where catalytic inhibition improves T-cell infiltration and suppresses tumor progression." (PMID 38914477, 2024). "The tumor growth was significantly suppressed by KD of EZH2, SUZ12, or integrin α11 which was given to the cells at initial implantation." (PMID 38664825, 2024). "Based on the spatial transcriptome profiles of SNUC tumor tissues, EZH2 appears to play a pivotal role in activating the PRC‐related chromatin remodeling process." (PMID 39565059, 2024). "Many tumor suppressor genes include promoter regions where EZH2 can be recruited by EZH2-interacting lncRNAs, which then use histone methylation to deactivate the transcription of those genes." (PMID 38730659, 2024). "Studies have shown that combining HMT inhibitors, such as EZH2 inhibitors, with immunotherapy, targeted therapy, chemotherapy, and endocrine therapy can result in synergistic anti-tumor effects, improving treatment outcomes." (PMID 39620228, 2024). "While the relative contribution of B cells and T cells in advanced AML is low, the impact of EZH2 inhibition on the tumor microenvironment should be carefully considered." (PMID 38339323, 2024). "Taken together, these findings imply that CC AM cells exhibit the properties of tumor-initiating cells and high proliferative activity, which can be suppressed by targeting EZH2." (PMID 38424060, 2024). "Tumor cells that were treated with EZH2 inhibitor alone or in combination with anti-PD1 had increased H2-K1, B2m, and Ifngr1 expression, and decreased expression of neutrophil-recruiting chemokines such as Cxcl3, Cxcl5, and Ppbp (a.k.a Cxcl7)." (PMID 38265267, 2024). "NEAT1 promotes tumor progression through two mechanisms: miRNA sponge or interaction with scaffold protein such as enhancer of zeste homolog 2 (EZH2)." (PMID 38646788, 2024). "Depending on the tumor type, both oncogenic and tumor-suppressor functions have been ascribed to EZH2, reflecting the pleiotropic effects of PRC2 on chromatin structure and gene expression." (PMID 38429303, 2024). "Operating as an oncogene, HOTAIR recruits EZH2 to catalyze the trimethylation of histone H3 at lysine 27 (H3K27me3), thereby repressing downstream tumor suppressor genes." (PMID 38522008, 2024). "Hypoxia-inducible factor 1-alpha (HIF-1α) is a key hypoxia responder that interacts with EZH2 to promote tumor progression." (PMID 38911968, 2024). "By inhibiting EZH2, tazemetostat reduces histone methylation, reactivating these suppressed genes and thereby inhibiting tumor growth." (PMID 39335494, 2024). "In contrast to the heterogeneous effects of HDACs on Treg cell populations, studies investigating Treg-mediated tumor immunosuppression observed a significant increase in EZH2 expression, specifically in tumor-infiltrating Treg cells." (PMID 38254784, 2024). "Effective reduction of both the in vitro CSC population and in vivo tumor volume can be achieved through combined inhibition of β-Catenin and EZH2." (PMID 38600608, 2024).
tumor (continued). "The oncogenic mechanisms of EZH2 in hematologic malignancies are complicated and depend on the tumor type." (PMID 38339397, 2024). "This measure is already relevant as EZH2 can act in a tumor-specific manner with oncogenic activity in most tumors, but a tumor suppressive role in a small subset of tumors, including cases of DMGs." (PMID 38183103, 2024). "Dual targeting of BMI1, a PRC1 component, and EZH2 has also hindered glioma stem cell growth both in vitro and in vivo, constraining tumor heterogeneity." (PMID 39766049, 2024). "More importantly, the combination of chemotherapeutic agents with the EZH2 inhibitor tazemetostat reversed chemotherapy-induced exosome-induced resistance in a tumor xenograft model in nude mice." (PMID 39372872, 2024). "Although many studies have presented EZH2 as an oncogenic factor, a tumor suppressive component has also been acknowledged and studied." (PMID 40135141, 2024). "Tumours were allowed to form, and mice (n = 5–7) bearing tumours of ~220 mm3 were treated for 28 days with the EZH2 inhibitor, GSK126, and the ATM inhibitor, AZD1390, or the combination of both drugs." (PMID 38519707, 2024). "SiHa-shEZH2 and HeLa-shEZH2 tumor xenografts models in nude mice were established to investigate EZH2-mediated epigenetic modulation of CCL22-CCR4 in vivo." (PMID 39513112, 2024). "Experimental findings from cancer mouse models demonstrate that genetic and pharmacologic inhibition of distinct epigenetic factors, such as CECR2, ALKBH5, and EZH2, impairs tumor progression by reducing TAM infiltration and immunosuppressive polarization." (PMID 39133578, 2024). "Considering the critical role that EZH2 plays in tumor angiogenesis, we examined the effect of GSK343 on eNOS and TGFβ expression by western blot analysis." (PMID 39204206, 2024). "EZH2’s role in cancer involves the extensive silencing of tumor suppressor genes via H3K27me3, enabling uncontrolled cell growth and the evasion of cellular safeguards against cancer formation." (PMID 39456545, 2024). "EZH2, a histone methyltransferase, primarily participates in suppressing aberrant tumor cell proliferation." (PMID 38612313, 2024). "Unsurprisingly, EZH2 is also involved in various hematological malignancies where it acts as an oncogene or a tumor suppressor." (PMID 39655332, 2024). "EZH2, the catalytic subunit of PRC2, is upregulated in various cancers and is frequently associated with accelerated tumour growth and a poor prognosis." (PMID 39471843, 2024). "EZH2 promotes cell proliferation, metastasis and drug resistance in several cancers by silencing the expression of tumour suppressors." (PMID 38635644, 2024). "In vitro experiments showed that Y646F mutation can change the substrate specificity of the EZH2 protein, improve the catalytic efficiency of H3K27 trimethylation, and promote tumor progression." (PMID 38773600, 2024). "Concomitantly, EZH2 KO tumors displayed significantly reduced growth in the primary tumor site (by 2 to 4 fold) and lung metastatic potential (by 10 fold)." (PMID 38791429, 2024). "EZH2 is overexpressed in many cancers, but both prooncogenic and tumor suppressive roles have be reported in the context of PDAC." (PMID 39739419, 2024). "Our study identifies a strong association between PAQR6 and angiogenesis-related pathways, particularly through its correlation with EZH2, a well-known oncogene involved in cell cycle regulation and tumor progression." (PMID 39742277, 2024). "Some findings have indicated that EZH2 suppresses tumor activity in myeloid malignancies and confirmed the adverse prognostic effects of EZH2-mutations." (PMID 40135141, 2024). "In both autochthonous and syngeneic grafts, EZH2 inhibition alone or with immunotherapy led to excellent tumor control." (PMID 38265267, 2024). "Bitler and colleagues used an EZH2 inhibitor (GSK126) to treat ARID1A-loss OCCC cells and found that ARID1A mutation status correlated with the response of tumor cells to EZH2 inhibitors." (PMID 38347608, 2024).
tumor (continued). "CARM1, for example, induced the methylation of BAF155, downregulating the expression of EZH2/BAF155 target tumor suppressor genes." (PMID 39678497, 2024). "It has been suggested that EZH2 has different functions in the timeline of tumor genesis and progression." (PMID 40135141, 2024). "EZH2 typically regulates tumor development through the classical pathway by forming the PRC2 complex which controls H3K27me3 deposition and represses transcription." (PMID 39655332, 2024). "According to research, EZH2 is involved in global transcriptional suppression and is overexpressed in multiple tumor entities, including ovarian, breast, bladder, and renal malignancies; hence, it is classified as an oncogene." (PMID 39719443, 2024). "Several studies have shown that highly expressed EZH2 is a key factor in mediating tumor progression." (PMID 39043634, 2024). "The tumor microenvironment with enhanced Myc and EZH2 gene expression observed in CDX was similar to the one observed in the biopsies of GB patients, further indicating the clinical relevance of our animal model." (PMID 38553638, 2024). "By activating PRC2, NEAT1 acts as an oncogene and promotes tumor development and progression in coordination with EZH2." (PMID 38646788, 2024). "It has been reported that suppressing EZH2 activity restores the expression of tumor suppressor genes and prevents cancer cell growth by inducing cell cycle arrest and apoptosis." (PMID 38836164, 2024). "MELK expression remained unchanged, EZH2 expression decreased and LATS2 expression was augmented in tumour tissues of nude mice injected with H1975 cells transduced with sh‐EZH2." (PMID 38652219, 2024). "In SNF5-deficient malignancies, PcG targets are extensively H3K27-trimethylated and repressed, where the deletion of the SNF5 tumour suppressor leads to increased expression of EZH2." (PMID 39471843, 2024). "The overexpression of EZH2 promotes tumor metabolic profile, cell proliferation, invasiveness, and the ability to metastasize, making it a key marker of tumor progression." (PMID 39120328, 2024). "In contrast, loss-of-function mutations in EZH2, which confer a poor prognosis, have been described in myeloid malignancies, T-ALL, suggesting a tumor-suppressive role for EZH2 in these cell lineages." (PMID 38473997, 2024). "EZH2 inhibitor induced cell cycle arrest, apoptosis and differentiation of tumor cells, and reduced tumor size." (PMID 38347129, 2024). "In osteosarcoma, circular PR domain zinc finger protein 2 (circPRDM2) positively modulated EZH2 expression in doxorubicin-resistant cells by targeting miR-760, inhibiting its tumour suppressive roles." (PMID 39703687, 2024). "EZH2 deletion enhances de novo KRAS-driven neoplasia following pancreatic injury, while increased EZH2 expression in patients with PDAC is correlated to poor prognosis, suggesting a context-dependant effect for EZH2 in PDAC progression." (PMID 39739419, 2024). "Of note, a CC AM cell subset with properties of tumor-initiating cells controlled by EZH2 is confirmed to be responsible for tumor recurrence, suggesting that targeting CC AM cells and EZH2 are promising approaches for AM treatment." (PMID 38424060, 2024). "Analysis of group differences between EZH2 tumors and normal tissues suggested that EZH2 expression was higher in the tumor group than in the normal group, and the median difference between the two groups was 1.303 (1.129–1.496, P < 0.001)." (PMID 39640777, 2024). "EZH2, the catalytic subunit of PRC2, is often upregulated in cancer, causing the silencing of tumor suppressor genes, DNA damage response genes, and mTOR pathway regulators." (PMID 39048945, 2024). "Coculture experiment further indicated that inhibiting EZH2 function significantly enhanced resistance to T‐cell‐mediated cytotoxicity on tumor cells." (PMID 38520088, 2024).
tumor (continued). "The in vivo drug trials with SCLC-LM mouse model demonstrated that PROTAC EZH2 degrader-1 plus VM26 or cisplatin/ VP16 inhibited H128-LM tumour significantly compared to VM26 or cisplatin/ VP16 alone (P < 0.01)." (PMID 38644473, 2024). "ERG, in concert with co-repressive proteins such as HDAC and EZH2, governs AR transcriptional activity, suppressing epithelial differentiation and fostering tumor progression." (PMID 38482016, 2024). "EZH2 overexpression and amplification increase as tumors progress to metastatic disease and can lead to the aberrant silencing of tumor suppressor genes." (PMID 38254784, 2024). "In vivo, EZH2 KO cells showed significantly reduced primary tumor growth and a 10-fold decrease in lung metastasis compared to WT cells, while EZH2 OE cells were unchanged." (PMID 38791429, 2024). "In mice with colon, prostate and skin cancers, knockdown of EZH2 resulted in a significant inhibition of tumor growth." (PMID 39080807, 2024). "Integrating EZH2 expression data from TCGA and GTEx, we observed significantly elevated EZH2 expression in tumor tissues compared to control tissues, with expression levels increasing with WHO grades." (PMID 38886655, 2024). "A pronounced increase in EZH2 expression was observed in tumor tissues relative to normal counterparts for all six cancer types." (PMID 39516467, 2024). "We found that the IC50 values of VP-16, carboplatin and VM26 in tumour cells treated with PROTAC EZH2 degrader-1 were significantly lower than those in tumour cells without PROTAC EZH2 degrader-1." (PMID 38644473, 2024). "This procedure resulted in 13 new clusters T0-T12 for the first subset, eight of which were identified as EZH2-positive tumor cell clusters (gray color code) and the rest as T-cells (green color code)." (PMID 39362842, 2024). "To ascertain the change in PRC2 occupancy at different promoter sets between primary and recurrent tumor, we performed EZH2 ChIPseq in longitudinal samples from one Up and one Down responder from our cohort." (PMID 38326875, 2024). "MALAT1 is known to bind to EZH2 and direct it to specific chromatin regions, leading to tumor suppressor gene repression, it can activate the EZH2-Notch1 and the PI3K/Akt signaling pathways." (PMID 38672463, 2024). "EZH2 typically silences multiple tumor suppressor genes through its histone lysine methyltransferase activity." (PMID 38764053, 2024). "On one hand, the upregulation of EZH2 in tumor cells allows the cells to escape the cytolytic activities of NK cells." (PMID 38254784, 2024). "Further, studies show the involvement of EZH2 in the regulation of tumor microenvironment and antitumor immune response in solid cancers, directly affecting immunotherapy efficacy." (PMID 38473229, 2024). "In CRC, HOTAIR upregulated the metabolic enzymes UPP1 by recruiting EZH2, thereby promoting the tumor progression, suggesting a novel metabolic axis for CRC therapy." (PMID 38696320, 2024). "The main function of EZH2 is to catalyze the methylation of H3K27Me3H3 histones, which inhibits the transcription of target genes, such as tumor suppressor genes." (PMID 39640777, 2024). "The role of EZH2 is critical in the regulation of diverse biological processes, such as tumor angiogenesis, cell apoptosis, EMT, as well as cell migration and invasion." (PMID 38600608, 2024). "Epigenetic modulating capacity and the anti-tumor response of administering EZH2 inhibitors, SHR2554, with an anti-PD-L1 antibody, SHR1701, is being tested in a trial involving patients with metastatic solid tumors and resistant B-cell lymphomas (NCT04407741)." (PMID 38333212, 2024). "For example, methyltransferase EZH2 promotes tumor glycolysis, while miR-138 inhibits EZH2 by decreasing H3K27 methylation." (PMID 39062577, 2024). "We used immunohistochemical analysis to quantify the protein expression levels of EZH2 and E‐cadherin in 34 tumor tissues of patients with SCLC." (PMID 39400978, 2024).
tumor (continued). "At the animal level, the EZH2 inhibitor can increase PD‐L1 levels in the tumor microenvironment and demonstrate a synergistic anticancer effect when combined with immune checkpoint blockade therapy." (PMID 38520088, 2024). "The enhancer of zeste homolog 2 (EZH2) seems to form an outstanding hub of cellular pathways promoting tumor viability." (PMID 38791289, 2024). "This relationship allowed us to demonstrate that either silencing IL-11Rα or debilitating the PRC2 complex through EZH2 inhibition can reduce primary tumor growth and prevent lung metastatic growth in vivo." (PMID 38886296, 2024). "In GBM, EZH2 contributes to both tumor cell proliferation and migration by methylating tumor suppressor genes and disruption of the TME cytokine profile." (PMID 39409893, 2024). "DYB‐03 is a newly screened dual‐target compound that targeting both HIF‐1α and EZH2 and displays significant anti‐tumor activity in vitro and in vivo, indicating the potential for clinical combination target therapy." (PMID 38072662, 2024). "Therapeutic strategies based on the biological function of BAP1 have been developed and evaluated for tumor patients harboring BAP1 deficiencies or alterations, such as histone deacetylase (HDAC) inhibitor, EZH2 inhibitor and PARP inhibitor." (PMID 39350280, 2024). "This connection is particularly noteworthy because it implies a critical role of EZH2 in cancer biology, influencing tumor initiation and progression." (PMID 38476362, 2024). "Agents that have shown anti-tumour activity in later lines in SS include trabectedin, pazopanib, regorafenib and anlotinib while immunotherapy and EZH2 inhibitors have produced dismal results." (PMID 39430097, 2024). "Meanwhile, the EZH2-mediated target gene CCND1 was upregulated in the tumor; CCND1 amplification is particularly common in ER-positive tumors and is associated with reduced survival in these patients." (PMID 38254989, 2024). "By inhibiting EZH2 and combining this with drugs that induce ferroptosis, we were able to effectively slow tumor growth." (PMID 39518098, 2024). "Studies have confirmed that EZH2 can serve as a substrate in tumor cells and be ubiquitinated and degraded by the proteasome system, playing a role in inhibiting tumor progression." (PMID 39043634, 2024). "Because of its recognized role in cancer progression, regulating EZH2 activity is considered an important anti-tumor therapeutic method." (PMID 38672463, 2024). "To overcome this drawback of EZH2 inhibitors in tumor treatment, we applied immunotherapy combined with EZH2 inhibitors to test the feasibility of synergic treatment using a murine xenograft tumor model." (PMID 38520088, 2024). "EZH2 facilitates tumor drug resistance during hypoxia with the activation of growth factor pathways and the dedifferentiation of tumor cells." (PMID 38911968, 2024). "For instance, EZH2, a histone methyltransferase, plays a pivotal role in tumor development and metastasis." (PMID 38834851, 2024). "Combining EZH2 inhibition with senescence-inducing therapy holds promise for achieving immune-mediated tumor control in PDAC." (PMID 39080807, 2024). "EZH2 regulating embryonic development promotes tumor proliferation, invasion, and metastasis through EMT regulation." (PMID 39400978, 2024). "Generally, those that disrupt the activity of the histone methyltransferase EZH2 can be regarded as tumor suppressors." (PMID 39055532, 2024). "In the in vivo model, GSK343 (5 mg/kg and 10 mg/kg) restored tongue tissue architecture and reduced tumor progression through EZH2 inhibition and Wnt/β-catenin signaling pathway modulation." (PMID 39204206, 2024). "In ovarian and colorectal cancers, EZH2 negatively correlates with tumor-infiltrating CD8+ T cells as well as patient outcomes." (PMID 38534385, 2024). "Nevertheless, the immunodeficient mice model we employed in this study can only assess the direct inhibition of PROTAC EZH2 Degrader-1 on tumour cells." (PMID 38644473, 2024).